MUC16 (mucin 16, cell surface associated)
Diseases named in the same sentence as MUC16 in open-access papers (continued):
Sharing a sentence is not in itself a finding about the gene and the disease.
cancer (continued). "Infact, the specific cytoplasmic staining of N-cadherin in both primary and metastatic tumor cancer cells suggests that the cytoplasmic domain links N-cadherin to MUC16 anchored on the cancer cell and is critical for the adhesive function required for motility and invasion." (PMID 37567918, 2023). "Development strategies similar to those used to generate NAV-001-PNU may potentially lead to improved therapeutic responses in patients with cancers overexpressing HIO factors such as MUC16/CA125." (PMID 37195923, 2023). "MUC16 overexpression promotes cancer cell proliferation and cancer cell resistance to therapy." (PMID 36765770, 2023). "Furthermore, ch5E6 exhibited a uniform pattern in recognizing 17 kDa cleaved form of MUC16 in both cancers." (PMID 37567918, 2023). "The remaining most frequent mutated cancer driver genes found in early-stage samples (KMT2C, ALK, BRCA2, GRM, ATM, and BRCA1) were not among those found to be the most frequently shared in late-stage samples (MUC16, CSMD3, KNT2C, NF1, LRP1B, SPEN, and TRRAP)." (PMID 37446001, 2023). "The findings are consistent with studies of various cancers, in which the loss of C1GALT1 and their specific chaperones, COSMC, contribute to increased truncation of O-glycans on several mucin proteins, including MUC4 and MUC16." (PMID 35207462, 2022). "MUC16, a well-known mechanical barrier gene, serves as a serum biomarker among various cancers." (PMID 35488336, 2022). "The shed extracellular domains of some membranous mucins (MUC1 and MUC16) can be detected in serum, and thus may be applicable for cancer diagnosis." (PMID 36553184, 2022). "However, in MPM, MSLN is known to be associated with epithelial–mesenchymal transition (EMT) and binding to mucin 16 (MUC16/CA125), which is associated with cancer progression and aggressiveness." (PMID 35884975, 2022). "A variable MUC16 status may have an impact on the progression of cancer, the prognosis of the disease, and treatment options, and it may also cause certain patients to have a natural resistance or sensitivities to treatment tests." (PMID 36051359, 2022). "Studies of human ovarian cancer have revealed that the cancer antigen CA125 can serve as a ligand of MSLN, and co-expression of MUC16 and MSLN is known to be associated with the invasion process of cancers, with MUC16 promoting the potential role of MSLN in tumor adhesion, and metastasis." (PMID 36358290, 2022). "89Zr-DFO-M16Ab bound specifically to MUC16-expressing cancer cells with an EC50 of 10nM." (PMID 36559316, 2022). "Additionally, we detected a large number of glycopeptides from MUC16, which is a key step toward better structural definition of this important cancer antigen." (PMID 35725833, 2022). "MUC16 is also known to play an anti-apoptotic role in cancer cells." (PMID 34681277, 2021). "While an infection is usually short-term and benign, other MS-identifiable proteins may indicate life-threatening diseases, such as the cancer marker MUC16." (PMID 33444735, 2021). "According to studies in other cancers, MUC16 may also be an important immunotherapy target for ESCC." (PMID 35127817, 2021). "Identification of a MUC16 fragment around 1kb or less with promoter activity that specifically controls CA-125 expression makes it possible for us to engineer the adenovirus type 5 for targeted cancer therapy." (PMID 34503075, 2021). "MUC16 is normally found on epithelial cells of the respiratory tract, female reproductive tissues, cornea and conjunctiva, while overexpression has been observed in various types of cancer." (PMID 34522225, 2021).
cancer (continued). "Our results provide evidence that antibody based Gal3 blockade may be a viable therapeutic strategy in patients with MUC16-expressing tumors, supporting further development of human blocking antibodies against Gal3 as potential cancer therapeutics." (PMID 33580170, 2021). "The consequence revealed that the high- and low- METAscore groups exhibited distinct mutation characteristics and the genes with a high mutation frequency in TTN, MUC4, PIK3CA, and MUC16 which all correlated with EMT and critical cancer pathways including PI3K/AKT and JAK2/STAT3 in CESC." (PMID 34277697, 2021). "Circ_MUC16 has been rarely investigated in human cancers, and its functions are largely unclear." (PMID 34837947, 2021). "In addition, the expression of MUC16 (cancer antigen 125, CA125) in the endometrium is thought to prevent uterine NK cells attacking the trophoblast and upregulation of MUC16 is typically found in ovarian, pancreatic, and other cancers." (PMID 32937961, 2020). "While cancer-specific exon–exon junctions may indeed be a source of neoepitopes, their sharedness across individuals and occurrence in cancer-relevant loci (e.g. EGFR, MUC16) are suggestive of underlying but as-of-yet unexplored biology." (PMID 34316681, 2020). "Hence, to build on our previous studies of MUC16 in PC and other cancers, we examined the expression status of Muc16 in the iKC model." (PMID 32709695, 2020). "MUC16 also prevents cancer cell recognition by NK cells; thus, enabling their survival." (PMID 33322519, 2020). "MUC16, the coding gene of mucin 16, promotes the proliferation and metastasis of cancer cells and may also have immunosuppressive effects." (PMID 33072607, 2020). "NF-κB has been involved in cytokine-mediated stimulation of MUC16 release in cancer cells." (PMID 31039761, 2019). "This type of deletion of MUC16 might help us to analyze the biological function of MUC16 more comprehensively with respect to cancer, especially in EOC." (PMID 30795761, 2019). "Interestingly, albeit previous studies have argued that some of the MUCs should be excluded as cancer genes based on biological relevance, there is much evidence supporting the link between MUC12 and MUC16 and cancer development and evolution." (PMID 31156702, 2019). "Similarly to MUC1 and MUC4, MUC16 overexpression in cancer promotes EMT, cell proliferation, migration and metastasis." (PMID 31514468, 2019). "MUC16 expression has been shown to be NF-κB-dependent in some cancer cell lines." (PMID 31039761, 2019). "In addition, MUC16 participated in cancer cell immune evasion by interacting with natural killer cells, B cells, and monocytes via Siglec-9." (PMID 30795761, 2019). "Surprisingly, patients with MUC3A, MUC4, MUC5B, MUC6, and MUC16 mutations had significantly better OS prognoses compared with those without mutations in several cancer types." (PMID 30107644, 2018). "In addition, peptides from mucin 16 (MUC16) were detected with decreased levels in the urine of cancer patients." (PMID 29588543, 2018). "Additionally, studies regarding the regulatory mechanisms driving abnormal MUC16 gene expression in cancer cells are very limited." (PMID 29552305, 2018). "After correcting for sequence length, MUC16 was not ranked in the top 10 of mutated genes for these cancers." (PMID 29552305, 2018). "MUC16 up-regulation may protect cancer cells from the immune response and prevent cancer cells from cytolysis." (PMID 29552305, 2018). "In contrast, the binding of the 5E6 mAb might not be affected by glycosylation and/or shedding and hence may serve as a more accurate MUC16 indicator in cancer cases." (PMID 29708979, 2018). "Recent reports have indicated that the retained carboxy-terminal (CT) fragment of MUC16 might play an important role in tumorigenicity in diverse types of cancers." (PMID 29708979, 2018). "These mAbs may help identify biological triggers and signaling events that induce the cleavage of MUC16 in cancer cells." (PMID 29708979, 2018).
cancer (continued). "MUC16 (CA125) is currently the best diagnostic marker for OC, however, the specificity and sensitivity of the marker is hampered by elevated expression in a number of benign diseases and other cancer types." (PMID 29854310, 2018). "In ovarian cancer, it has been shown that mesothelin binds to ovarian cancer antigen MUC16 (CA-125) and may contribute to dissemination into the abdominal cavity." (PMID 28460459, 2017). "In cancers such as ovarian and breast, there was a direct correlation between the staining intensity for both cytokines and MUC16." (PMID 26918940, 2016). "In addition, overexpression of MUC16 has also been observed in endometrial, breast and lung cancers." (PMID 27382435, 2016). "Phenotypically, Meso64-TR3 is more closely related to non-targeted TR3, evident by indistinguishable activity profiles on MUC16-deficient cancers and similar thermal stability characteristics." (PMID 27120790, 2016). "As similar to MUC1 and MUC16, MUC3A is also a membrane-associated mucin and maybe applied in serodiagnostic tests to diagnosis and monitor cancers." (PMID 27374181, 2016). "Taken together, the strong death-inducing properties of Meso64-TR3 were found to depend on membrane tethering to the cancer biomarker MUC16 and was confirmed to be consistent with key attributes of death receptor-mediated, caspase-dependent forms of programmed cell death - apoptosis." (PMID 27120790, 2016). "Clearly, further studies are required to determine the exact mechanism of action, and whether MUC16-specific targeting of lectins such as siglec, selectins, or galectins were involved in cancer modulation." (PMID 27382435, 2016). "Disruptions in glycosylation may readily expose MUC16 for proteolytic cleavage of the extracellular domain, and thus potentiate signaling of the cytoplasmic tail to drive progression of cancer." (PMID 27483328, 2016). "Developing methods to manipulate MUC16 expression could provide new approaches to treating cancers whose growth or metastasis is characterized by elevated levels of TMs, including MUC16." (PMID 26918940, 2016). "Thus our study reveals MUC16-Cter-JAK2-LMO2/NANOG axis to be a novel pathway responsible for mediating enrichment of PC cancer stem-like cells." (PMID 25691062, 2015). "Altogether, the present study provides insightinto the cleavage of MUC16 that is critical towards understanding its functionalsignificance under physiological and pathological conditions and subsequent therapeutictargeting in multiple cancer types." (PMID 26044153, 2015). "Soluble Meso-TR3 targets the cancer biomarker MUC16 in vitro and in vivo." (PMID 24447304, 2014). "Importantly, the two signals overlapped (“merge”) and suggest that Meso-TR3 co-localizes with the mesothelin receptor MUC16 on the same cancer cell membrane." (PMID 24447304, 2014). "Our work demonstrates that MUC16-Siglec-9 interaction protects cancer cells from NK cell attack." (PMID 24886523, 2014). "Siglec-9 is also expressed on monocytes and MUC16 promotes binding of monocytes to cancer cells." (PMID 24886523, 2014). "In this study, we investigated the relationships between mucin expression and clinicopathologic factors in 60 SBC cases, in which expression profiles of MUC1, MUC2, MUC3, MUC4, MUC5AC, MUC6 and MUC16 in cancer and normal tissues were examined by immunohistochemistry." (PMID 24722639, 2014). "Overall, these data show that a significantly higher concentration of Meso-TR3 is required to achieve equivalent biological effects on MUC16-deficient cells and, at equipotent doses, Meso-TR3 is substantially more effective than TR3 on MUC16-positive cancer cells." (PMID 24447304, 2014). "These are the first studies to show a potential biological role for MUC16 in non-cancer cells." (PMID 24886523, 2014).
cancer (continued). "Recent studies highlighted the possible mechanisms by which MSLN could play an active role in cancer progression; it was shown to interact with MUC16, and to activate the p38 pathway, leading to the selective induction of matrix metalloproteinase (MMP)-7." (PMID 24465798, 2014). "The MUC16 gene is located at 19p13, which is altered in a variety of cancers, especially ovarian." (PMID 24551091, 2014). "Due to its extended structure and overall negative charge (due to the presence of terminal sialic acid residues), MUC16 may inhibit intimate interactions between NK and cancer cells." (PMID 24886523, 2014). "In fact, it was used to deliver immunotoxins to specific cancer cells, or, such as for the case of the monoclonal antibody MORAb-009, to arrest cancer progression by direct inhibition (e.g. disrupting the interaction with MUC16)." (PMID 24465798, 2014). "The detection of CA 19-9 on MUC16 had performance statistically equivalent to that of total CA 19-9, with a detection of early-stage cancer at 82% sensitivity and 77% specificity, and a detection of late-stage cancer at 90% sensitivity and 77% specificity." (PMID 22220206, 2011). "In addition to serving as a cancer biomarker, MUC16 is also important in promoting the metastasis and growth of ovarian tumors." (PMID 20497550, 2010). "Furthermore, mesothelin, acting as a MUC16 functional partner in cancer development, may become more prone to bind with these mutant variants." (PMID 40478193, 2025). "Interestingly, the MUC16 oncogene, which mediates proliferation and migration, and MMP13, implicated in invasion, metastasis, and angiogenesis, show higher mutation rates in LoY tumors of specific cancer types, such as renal papillary cell carcinoma." (PMID 39594721, 2024). "We speculated that CAR-NK cells targeting MUC16 could also have some effect in cancer therapy." (PMID 38758220, 2024). "However, mutations in genes that are involved in immunoresistance of cancers such as ASXL, MUC4, MUC16 or MUC17 may negatively affect the efficacy." (PMID 36980598, 2023). "However, mutations of MUC4 and MUC16 are described predominantly in TET histotypes rich in cancer cells and not in thymocyte-rich tumors, suggesting the actual presence of the mutation." (PMID 37671056, 2023). "Notably, mutations of TTN and MUC16 were associated with the TMB and could predict the immunotherapy efficacy in GC and pan‐cancer." (PMID 35621244, 2023). "Herein, we establish the utility of targeting a post-cleavage generated, surface-tethered oncogenic MUC16 carboxy-terminal (MUC16-Cter) domain by using a novel chimeric antibody in human IgG1 format, ch5E6, whose epitope expression directly correlates with disease severity in both cancers." (PMID 37567918, 2023). "MUC16 upregulation may help in cancer cell protection from cytolysis and the immune response." (PMID 36552994, 2022). "According to certain research, MUC16 could be a viable therapeutic target for cancer patients." (PMID 36552994, 2022). "Siglec-9 is expressed on the surface of B-cells, granulocytes and NK cells, and its interaction with membrane-bound MUC16 may pose a barrier to NK cell interaction with cancer cells, while interaction with soluble MUC16 downregulates the activating Fc-γ receptor CD16 on NK cells." (PMID 32937961, 2020). "In order to further study the mechanism of cytoplasmic p120ctn in modulating MUC16 promoted proliferation and migration, we referred to a lot of related researches and found that the cytoplasmic p120ctn could affect cancer development through modulating Rho GTPases activation." (PMID 30795761, 2019). "However, the functional characteristics and signalling capabilities of MUC16 that contribute to these fibrotic processes in cancer remain unclear." (PMID 31514468, 2019).
cancer (continued). "Given the transmembrane nature of MUC16 and the present demonstration of the new biological role and cellular mechanisms may augment additional therapeutic strategies in the future for the treatment of this deadly cancer." (PMID 27382435, 2016). "Interestingly, expression of as few as 114 amino acids from the C-terminal portion of MUC16 is sufficient to increase soft agar growth and the invasive properties of cancer cells, supporting a significant role for the signaling capacity of the C-terminal portion of MUC16." (PMID 27483328, 2016). "In the context of cancer biomarkers, proteins such as CA125/MUC16, Mesothelin and Enolase 2 are increasingly used not only for diagnosis and monitoring, but also as targets to evaluate therapeutic impact and prognosis in oncology." (PMID 41515404, 2025). "MUC16, also known as CA125, is a large transmembrane mucin that exhibits aberrant expression in a variety of cancers, including lung cancer." (PMID 40655139, 2025). "While prevalent in FL and other cancers, we have only recently begun elucidating the role of CA125/MUC16 in tumor biology and immunity." (PMID 40583906, 2025). "mRNA expression of FAM83A, LY6D, MET, MUC16, MYEOV, and WNT7A were significantly elevated in cancer than healthy tissues (P<0.05)." (PMID 38169540, 2024). "The comprehensive delineation of mucin dysregulation in cancer now leads to a focused analysis of MUC1 and MUC16, examining their intricate molecular interactions and pivotal influence in oncological processes." (PMID 38361923, 2024). "Regarding the immunomodulatory capacity of these proteins, MUC1 and MUC16 were found to mask TLR signaling, resulting in the reduction of effector T cell functions, therefore enhancing cancer cell immune evasion and metastasis." (PMID 39744399, 2024). "The capacity of nanobody S1 to target MSLN+ cells was evaluated by flow cytometry on a panel of cancer cell lines from different cancers, expressing various levels of MSLN and of its ligand MUC16." (PMID 37388728, 2023). "In Boyden chamber assay, ch5E6 inhibited the migration of MUC16 expressing pancreatic (SW1990, P = 0.0282) and lung (SW1573, P = 0.0568) cancer lines." (PMID 37567918, 2023). "Accumulating evidence suggests the contribution of mucins, specifically MUC16, in inducing the EMT phenomenon, which is usually opted by the cancer cells for acquiring features including enhanced invasion, migration, evade apoptosis, and rapid progression." (PMID 37567918, 2023). "MUC16, also known as cancer antigen 125 (CA125), is a novel biomarker and a novel target for human cancers." (PMID 35522895, 2022). "Proteins or glycoproteins that are cancer biomarkers, such as prostate-specific antigen (PSA), carcinoembryonic antigen (CEA), cancer antigen 19-9 (CA 19-9), or mucin 16 (CA-125/MUC16), are relatively large molecules." (PMID 35407220, 2022). "Here, we report for the first time the development of a fully human monoclonal anti-MUC16 antibody for the purpose of PET imaging and targeted radioimmunotherapy of MUC16-expressing cancers." (PMID 36559316, 2022). "C1GALT1 has a modulatory effect on expression of target glycoproteins such as MUC16, Muc5Ac, and MUC1, and regulates progression of certain types of cancer." (PMID 35864552, 2022). "Intravenous or intraperitoneal administration of MUC-16-CAR-T cells can inhibit the growth and development of cancer cells and mouse tumor-bearing solid models." (PMID 35833132, 2022).